TEAD1 (TEA domain transcription factor 1)
Diseases named in the same sentence as TEAD1 in open-access papers (continued):
Sharing a sentence is not in itself a finding about the gene and the disease.
tumor (continued). "YAP1 and TEAD1 transcript levels were effectively found to increase in GBM tissues, whereas those of TAZ remained unchanged among the healthy anti‐tumour tissue data analysed." (PMID 39718433, 2024). "The results constantly showed that PCa patients with triple low expression of ITGA1, ITGA2 and TEAD1 demonstrated higher Gleason score, PSA levels, advanced tumor stages and lymph node metastasis." (PMID 38169150, 2024). "This comparison showed a very high degree of overlap in the percentage of target loci where VGLL1 bound compared to those targets previously identified for TEAD1, TEAD2, TEAD3, and TEAD4 (p < 10e-370 for all 3 tumor cell lines)." (PMID 38912065, 2024). "Sunet al. proved that TEAD1 can regulate the transcription of HIF1A and further promote tumor glycolysis." (PMID 37723874, 2023). "Interaction with these partners such as TEAD1–4, RUNX, KLF4 and AP-1 promotes tumor growth, metastasis and immune evasion." (PMID 33097055, 2020). "Our results reveal a novel mechanism of acquired trastuzumab resistance mediated by two pivotal effectors of the Hippo tumor suppressor pathway: the transcriptional co-activator YAP1 and the transcription factors TEAD1-2." (PMID 32365528, 2020). "This highlighted TEAD1/4 as the most highly and uniquely overrepresented motifs in GSC tumor-specific peaks." (PMID 30275445, 2018). "Mechanistically, we found that VGLL4 interacts with TEAD1 via its second TEAD-interacting domain (TDU2), selectively antagonizing the TEAD1-YAP1 transcriptional complex and, therefore, YAP-dependent tumor growth." (PMID 28733631, 2017). "For example, the anti-TEAD4 antibody also detected overexpression of Flag-TEAD1–3 in HEK293T cells, indicating that we detected all TEAD proteins in tumor specimens using this antibody in general." (PMID 25970772, 2015). "Additionally, EFHD1 overexpression reduced nuclear YAP1, nuclear TAZ, and TEAD1 levels, thereby preventing YAP1/TAZ nuclear translocation and interaction with TEAD1, a key process in tumor progression." (PMID 39895792, 2025). "It is important to note that the soma-germ transition induced by MS also coincided with inactivation of the Hippo tumor-suppressor pathway and the transition of YAP1 in the cell nucleus, colocalising and activating TEAD1, along with the nuclear activation of OCT4A." (PMID 36834647, 2023). "Patients aged <1 year with VGLL2, SBF, TEAD1, and NCOA2 gene fusions had a better prognosis, whereas patients with a MYOD1 gene mutation demonstrated stronger tumor aggression and higher mortality, regardless of age." (PMID 36686750, 2022). "Hence, based on this data, 67% TOR on TEAD1, 30–40% decrease in the YAP1-TEAD transcription score, and 60% downregulation of CYR61 protein levels are sufficient to achieve tumor regression in the MPM NCI-H226 model." (PMID 35689194, 2022). "In this study, YAP and TEAD1 are co-localized at the promoter regions of CTGF (CCCTC-Binding Factor), MYC, EDN1 (Endothelin 1), and EDN2, leading to cancer cell proliferation and migration in vitro as well as tumor growth in xenograft model." (PMID 35602596, 2022). "Collectively our results suggested that EGFR, MAP2K1, mTOR, TEAD1, and YAP1 could mediate invasive tumor phenotypes and produce worse prognoses via mechanisms involving both the T-cell exclusion and dysfunctional phenotypes." (PMID 35655775, 2022). "Collectively our results suggested that EGFR, MAP2K1, mTOR, TEAD1, and YAP1 could mediate invasive tumor phenotypes and worsen prognoses via mechanisms involving both T-cell exclusion and dysfunctional phenotypes." (PMID 35655775, 2022). "Multiple mechanisms, such as the TEAD1 signalling pathway, an overexpression of Hedgehog (Hh), suppression by miR-1285-3p, and circFAT1 are involved in the regulation of YAP1 in tumours." (PMID 33803512, 2021).
tumor (continued). "In tumours, this resulted in melanocytic phenotype cells that still expressed high levels of MITF, but had up‐regulated EMT and invasive signatures and corresponding transcription factors such as TEAD1 and AP1 factors." (PMID 32145051, 2020). "The YAP1/TEAD1 protein complex had the capability to influence downstream cytoskeletal proteins by regulating SRC transcription; therefore, it converts NF to CAF, and CAF can significantly promote tumour growth and metastasis." (PMID 32066485, 2020). "According to the RISH and IHC analyses, the tumor from the MDNP/dCas9–miR‐524‐treated mice exhibited remarkably higher miR‐524 expression level, which led to significant inhibition of the expression of Smad2, Hes1, and Tead1." (PMID 30643726, 2019). "To investigate whether YAP-mediated mTOR activation contributed to tumor initiation, we treated KEY primary cells with siRNAs targeting Yap/Taz and Tead1/Tead4 as well as small molecule mTOR (INK128) and YAP-TEAD (VT104) inhibitors, and observed significant reductions in clonogenic growth." (PMID 39779672, 2025). "To explore the possible role of protein lactylation in driving tumor cell proliferation, we then focused on the Hippo signaling pathway, in which several components or regulatory proteins, such as ACTG1, MOB1A, PPP1CA, YAP, and TEAD1, were found to be lactylated." (PMID 38512451, 2024). "Furthermore, ChIP analysis proved that YAP1/TEAD1 could co-regulate the transcription of HIF1A and further promote tumour glycolysis." (PMID 33218358, 2020). "Together with the previous observation that TEAD1 plays a crucial role in the regulation of OS cell proliferation, these results strongly support the hypothesis that the YAP/TEAD axis could represent a promising target to inhibit primary OS tumor growth." (PMID 33419295, 2020). "We confirmed induction of TEAD1/2/4, but not TEAD3, by qPCR analysis in Apc mutant intestinal organoids in vitro, ApcMin mutant tumours in vivo and in Apcfl/fl knockout intestinal crypts in vivo." (PMID 33950519, 2021).
cancer (57 papers, 2008 to 2026). A tumor composed of atypical neoplastic, often pleomorphic cells that invade other tissues. "We assessed pan-cancer expression, methylation, and mutation profiles of TEAD1 to determine its prognostic significance in clinical settings." (PMID 40539054, 2025). "TEA domain transcription factor 1 (TEAD1), the first member identified within this family, has been implicated in various cancers due to its deregulation." (PMID 40539054, 2025). "TEAD1/Tef-1, encoded by TEAD1 gene, has garnered extensive attention due to its critical role in multiple cancers." (PMID 40539054, 2025). "Last, a cancer-associated YAP fusion protein exhibits substantially different biophysical behavior than either YAP or TEAD1." (PMID 40712036, 2025). "Noticeably, TEAD1 knockdown strongly accentuated the proliferation deficiency of siROBO3 treated cancer cells, pointing to sensitization of these cells to further interferences with the YAP1-signaling." (PMID 36057630, 2022). "These RNA modifiers regulate the expression of multiple oncogenes such as fizzy-related-1, forkhead box protein C2, Grb associated-binding protein 2, and TEA domain transcription factor 1, facilitating the pathogenesis and progression of cancers." (PMID 35562754, 2022). "Furthermore, we found that TEAD1 expression was closely associated with clinical outcomes across multiple cancers; these findings are consistent with existing literature." (PMID 40539054, 2025). "In addition, TEAD1 was also significantly associated with genes associated with RNA methylation modification in pan-cancer." (PMID 40539054, 2025). "Furthermore, TEAD1 directly regulates the transcription of Mesothelin (MSLN) that is highly expressed in several cancers and is a good candidate for a diagnostic marker." (PMID 23029054, 2012). "Among these, CpG sites associated with ZNF667, TEAD1, HDAC4, MSI2, and CCM2 were predominantly hypermethylated, while malignant tumors overall exhibited lower methylation levels compared to the benign group." (PMID 41597272, 2026). "The results showed that in various cancers, TEAD1 mRNA expression was significantly positively correlated with its CNV and negatively correlated with its methylation level." (PMID 40539054, 2025). "Previous studies have demonstrated that TEAD1 can function as either a promoter or a suppressor of tumorigenesis, depending on the specific cancer context." (PMID 40539054, 2025). "Our findings suggest that TEAD1 is differentially expressed across various cancer types and can act as an independent prognostic factor for multiple cancers." (PMID 40539054, 2025). "TEAD1 and TEAD4 were specifically recognised and targeted, with both TEAD1 and TEAD4 implicated in the progression and development of various cancers." (PMID 40744733, 2025). "In this study, we conducted a comprehensive analysis of TEAD1’s pan-cancer expression levels, prognostic significance, epigenetic alterations, and immune landscape." (PMID 40539054, 2025). "It is worth noting that the TEAD1 low expression group has higher infiltration of immune cells into tumors and killing of cancer cells activity." (PMID 40539054, 2025). "Understanding the complex mechanisms by which TEAD1 contributes to cancer pathogenesis is crucial and holds significant promise for the developing of targeted and personalized therapeutic strategies." (PMID 40539054, 2025). "TEAD4, a member of the TEA (Transcriptional enhanced associate) domain-containing transcription factors family including TEAD1, 2, 3, and 4, has been reported to possess oncogenic effects in various cancers." (PMID 39735666, 2025). "To expand the sample size and obtain more reliable results, we integrated normal samples from the GTEx database and observed widespread dysregulation of TEAD1 in more than four-fifths of cancer types." (PMID 40539054, 2025). "Nevertheless, the potential role of TEAD1 in cancer-related epigenetic alterations, immunological characteristics, and prognosis remains ambiguous." (PMID 40539054, 2025).
cancer (continued). "This study thoroughly investigates the multifaceted roles of the TEAD1 gene in cancer biology, particularly in LIHC." (PMID 40539054, 2025). "To reveal the mechanisms leading to dysregulated TEAD1 expression, we evaluated the CNV and methylation levels of TEAD1 in pan-cancer." (PMID 40539054, 2025). "Another recurrently associated transcriptional regulator is TEAD1, a transcription factor that recruits the YAP/TAZ coregulators to promote cancer cell proliferation, survival, and stemness." (PMID 38723607, 2024). "While TEAD1 is ubiquitously expressed in most cancers, the expressions of TEAD2, TEAD3, and TEAD4 are more selective." (PMID 38067201, 2023). "Aberrant expression and/or splicing of DST (also known as BPAG1), TEAD1 and THOC5 are associated with neurological disorders and cancer." (PMID 37026480, 2023). "Consistently, TEAD 1‐4 were increased in carcinoma cells, with TEAD1 being highly expressed in SqCC/Y1, TEAD1‐4 in H314 and H413, and TEAD2‐4 in H376." (PMID 35000271, 2022). "Further, YAP1 interaction with transcription factors such as TEAD1-4 in the nucleus can promote cancer cell proliferation, anchorage-independent growth, EMT and metastasis." (PMID 25473897, 2015). "Although the regulation of TEAD1 transcription is poorly understood so far, its expression is misregulated in several types of cancers." (PMID 23029054, 2012). "Taken together our data reveal a new, Livin-dependent, apoptotic role for TEAD1 in mammals and provide mechanistic insight downstream of TEAD1 deregulation in cancers." (PMID 23029054, 2012). "The data presented in our study, in which a similar apoptotic resistance and Livin up-regulation is observed upon TEAD1 knockdown or overexpression, provide a conceptual framework to reconcile such discrepancies observed in different cancer types." (PMID 23029054, 2012). "Furthermore, TEAD1, another transcriptional regulator found to be activated in this study, is frequently overexpressed in various cancer cells." (PMID 41154628, 2025). "Moreover, we observed that epigenetic changes involving TEAD1 are highly heterogeneous among several cancers; abnormal methylation and copy number variations were associated with a poor prognosis in multiple malignancies, especially in LIHC." (PMID 40539054, 2025). "Furthermore, we analyzed the pan-cancer immunological landscape of TEAD1, with a particular focus on liver hepatocellular carcinoma (LIHC), using correlation analysis." (PMID 40539054, 2025). "In addition, we evaluated the expression of TEAD1 in pan-cancer at spatial transcriptome resolution." (PMID 40539054, 2025). "In addition, we evaluated the correlation between TEAD1 and the clinical stage of cancer using the TISIDB database." (PMID 40539054, 2025). "Our study found that gene PATJ may play an important role in shaping the occurrence and progression of cancer and that its regulator TEAD1 could serve as a specific marker for LUAD diagnosis." (PMID 41415280, 2025). "This study aims to clarify the function and potential mechanisms of action of TEAD1 in cancer." (PMID 40539054, 2025). "According to previous reports, YAP is known to recruit transcription factors TEAD1-4, RNA polymerase, the mediator complex, and other factors to establish a transcription hub within the nucleus, facilitating oncogenic transcription during cancer progression." (PMID 38223760, 2024). "In addition to 33 direct YAP targets (such as BIRC5, CDH4, TEAD1) previously established in epithelial and cancer cells, 1,027 genes were newly identified to be YAP signatures in neutrophils." (PMID 36921037, 2023). "They regulate expression of majority their target genes by interacting with TEAD1-4 transcription factors and are frequently deregulated in several cancers, where they regulate multiple aspects of cancer development including cancer growth, metastasis and chemo/immunotherapy resistance." (PMID 36523977, 2022).
cancer (continued). "As the terminal effectors of the Hippo pathway, the transcriptional coactivators YAP1/TAZ and the transcription factors TEAD1–4 present exciting opportunities to pharmacologically modulate the Hippo biology in cancer settings, inflammation and regenerative medicine." (PMID 34685695, 2021). "The expression of miR‐524 can restrain the proliferation of cancer cell via targeting and inhibiting the expression of Smad2, Hes1, and Tead1 which are essential proteins for transforming growth factor‐β (TGF‐β), Norch, and Hippo signaling pathways, respectively." (PMID 30643726, 2019). "Increased YAP levels have been reported in a large variety of cancers, and might interfere with the role of TEAD1 in apoptosis." (PMID 23029054, 2012). "However, this was not a significant factor in multivariate analysis because of a strong correlation with Gleason score, with diffuse TEAD1 staining found in predominately high Gleason cancers." (PMID 19002168, 2008). "Our high-resolution imaging studies showed that one such cancer fusion, YAP-TFE3, is less mobile and binds DNA longer than either YAP or TEAD1 and, like YAP, its nuclear behavior is highly dependent on TEADs." (PMID 40712036, 2025). "ReMap ChIP-seq data confirmed the strong binding of TEAD1/4 and YAP at the promoter and intron 1 of VSIR, as well as at the promoter of PD-L2 in a variety of cancer cells." (PMID 40940864, 2025). "We identified a total of 1251 and 1313 cancer patient samples carrying the oncogenic alterations for the Hippo pathway genes and YAP/TAZ/TEAD1-4, respectively." (PMID 39572544, 2024). "A pan-cancer differential TEADs expression identified a high expression of TEAD1, TEAD2, TEAD3, and TEAD4 in 3, 6, 5, and 12 types of cancer tissues, respectively." (PMID 38607003, 2024). "To study Hippo signaling dysregulation in human cancers, we analyzed the somatic alterations of Hippo pathway components, effectors YAP/TAZ, and transcription factors TEAD1-4 (hereafter referred to as Hippo signaling) in The Cancer Genome Atlas (TCGA)." (PMID 39572544, 2024). "In OS and HCC, under-expressed miR-1294 inhibits cancer cell apoptosis by upregulating pyruvate kinase M2 (PKM2) in OS and TEA domain transcription factor 1 (TEAD1) and pim-1 proto-oncogene in HCC." (PMID 37303740, 2023). "This revealed peaks for TEAD1 and TEAD4 on both KISS1 and CXCL8 promotors, suggesting that within cancer cells, TEAD transcription factors facilitate the expression of genes both up‐ and down‐regulated on NF2 loss." (PMID 36740402, 2023). "Consistent with links between the blue module and cancer, we find that many blue module hub genes, such as Moesin (MSN), YAP1, TEAD1, and WWTR1 are well known for their role in cancer and mediate the EMT." (PMID 36879821, 2023). "Previous studies have shown that GLUT1 transcription is regulated by TEA domain family member 1 (TEAD1), HIF-1α, and c-Myc in proliferative cells like cancer cells and fibroblasts." (PMID 35133975, 2022). "Differential hydroxymethylation is found in thousands of genes, most significantly in genes related to pancreas development or function (GATA4, GATA6, PROX1, ONECUT1, MEIS2), and cancer pathogenesis (YAP1, TEAD1, PROX1, IGF1)." (PMID 33077732, 2020). "We observed a significant correlation between TEAD1 and LIHC in cancer types." (PMID 40539054, 2025). "In cancers, the intracellular accumulation of lactate leads to the import of AARS1 into the nucleus, where it lactylates the K90 site of YAP and the K108 site of TEA Domain Transcription Factor 1 (TEAD1)." (PMID 40264038, 2025). "Antiproliferative activity of IAG933 in a panel of 103 cancer cell lines showed significant overlap with the genetic sensitivity profile of averaged short hairpin RNA (shRNA) knockdown results from Project DRIVE30 for YAP, TAZ and TEAD1." (PMID 38565920, 2024). "Furthermore, previous studies have shown that VGLL1 can directly interact with TEAD1 and TEAD4 in cancer cells." (PMID 38912065, 2024).
cancer (continued). "TEAD1 is a key TF in various oncogenic signaling pathways, including the Hippo, Wnt, TGFβ, and EGFR pathways, and plays critical roles in EMT, metastasis, drug resistance, and cancer stem cells." (PMID 35999456, 2022). "In contrast, we observed little or no TEAD1 staining in cancer tissues." (PMID 38169150, 2024).
infection (5 papers, 2021 to 2025). The state of being infected such as from the introduction of a foreign agent such as serum, vaccine, antigenic substance or organism. "Furthermore, we knocked down and overexpressed TEAD1 in foam cells via infection with si‐TEAD1 and Ad‐TEAD1, respectively, to verify whether TEAD1 regulates lipid accumulation via activated YAP/AMP‐activated protein kinase signaling." (PMID 40089857, 2025). "ChIP-seq experiments for TEAD1, CTCF, and H3K27ac were performed in duplicate in uninfected and HCMV-infected conditions (48 hr post-infection)." (PMID 40928347, 2025). "Compared to the control group, the infection of HCMV significantly reduced the mRNA expression of Mst1, Mst2, SAV, Lats1, Lats2, Mob1, YAP1, TAZ, TEAD1-4 genes and YAP protein expression in the Hippo-YAP pathway." (PMID 34717661, 2021). "Notably, only TEAD1 was differentially expressed among the four TEAD family members, with a 3.7-fold decrease upon infection (adjusted p-value: 1.9 × 10–29)." (PMID 40928347, 2025). "We thus examined the protein expression levels and phosphorylation status of YAP1 (pYAP1) with and without infection, along with the expression of HCMV proteins IE1/2, TEAD1, and the H3K27ac histone mark in uninfected and infected cells." (PMID 40928347, 2025).